CASR (calcium sensing receptor)
Diseases named in the same sentence as CASR in open-access papers (continued):
Sharing a sentence is not in itself a finding about the gene and the disease.
kidney stones (continued). "Notably, we observed low urinary oxalate in our rat nephrolithiasis model treated with GdCl3 compared with group B; one possible explanation for this finding is that CaSR increased free calcium, which binds to oxalate and thus reduces urinary oxalate." (PMID 33678127, 2021). "The results suggest that CaSR might play significant roles in the induction of nephrolithiasis in rats through ROS production and regulation of PS ectropion, stone-related protein expression, and composition of urine in urine." (PMID 33678127, 2021). "This evidence indicates that CASR may be involved in kidney stone formation not only via controlling the calcium concentration, but also via regulating the urine pH." (PMID 31754202, 2019). "Although we did not observe an association of rs7627468 in CASR with the susceptibility to nephrolithiasis, we found the rs7627468 correlate with the pH value and calcium/creatinine ratio of urine." (PMID 31754202, 2019). "In conclusion, this study identifies 20 loci linked to kidney stone formation, seven of which are have not previously been reported to associate with kidney stone disease, and reveals the importance of vitamin D metabolism pathways and enhanced CaSR-signaling in the pathogenesis of nephrolithiasis." (PMID 31729369, 2019). "Associations between vitamin D signaling pathway genes and nephrolithiasis-related ESRD as well as interactions with CASR rs7652589 were also not observed." (PMID 27739473, 2016). "Taken together, this suggests that the effect of CASR on kidney stones is complex." (PMID 26272126, 2015). "Another important polymorphism of CaSR gene is Arg990Gly located in Exon 7 and associated with hypercalciuria in patients with and without kidney stones." (PMID 26107257, 2015). "A similar pattern is observed at CASR where we observe two uncorrelated signals, one located in intron 1 of the CASR gene associating with kidney stones and the other at the 3′-end of the gene associating strongly with serum calcium but not with kidney stones." (PMID 26272126, 2015). "For example, specific polymorphisms of the genes encoding vitamin D receptor (VDR), vascular endothelial growth factor (VEGF), androgen and estrogen receptors, calcium-sensing receptor (CASR), matrix Gla protein (MGP), and fibronectin (FN 1) were suggested to be a risk factor for nephrolithiasis." (PMID 24023817, 2013). "The major complications of primary hyperparathyroidism, namely skeletal manifestations (presence of osteopenia or osteoporosis) and nephrolithiasis, were also evaluated: patients with and without CASR gene polymorphisms didn’t show a significant difference in their prevalence." (PMID 40870022, 2025). "The calcium-sensing receptor (CASR) plays a crucial role in calcium homeostasis, and single-nucleotide polymorphisms (SNPs) in the CASR gene may contribute to the occurrence and recurrence of nephrolithiasis." (PMID 40630330, 2025). "There is growing evidence that CaSR may play a role in increasing the propensity for kidney stones." (PMID 33678127, 2021). "Finally, we summarized the extensive literature on the link between vascular calcification and nephrolithiasis, and reviewed the possible hypothesis that may explain this link and the role played by the CaSR in this connection." (PMID 33808324, 2021). "Thus, we have conducted this narrative review, which is based on the articles retrieved from the databases Medline and PubMed using the search terms “calcium signaling”, “calcium sensing receptor”, “vascular calcification”, “kidney stone” and “nephrolithiasis” for the topic." (PMID 33808324, 2021). "As the CaSR plays a pivot role in the regulation of calcification in various organs, a dysregulation in Ca2+ signaling could be considered as the connection between vascular calcification and nephrolithiasis." (PMID 33808324, 2021).
kidney stones (continued). "The fasting urinary calcium/creatinine ratio was measured in samples of first morning urine for these 12 patients: three had elevated urinary calcium (none with a history of kidney stone) and two had low urinary calcium, but none of these subjects had a CasR mutation." (PMID 31979085, 2020). "Therefore, the development of kidney stones despite elevated PTH levels in patients with CKD may reflect a problem with PTH or calcium sensing receptor function in the renal tubule." (PMID 30760766, 2019). "Therefore, the present study was designed to examine the possible effects of CaSR in a model of CaOx-induced nephrolithiasis and to provide direct physiological and biochemical evidence of whether CaSR is involved in this process." (PMID 27965733, 2016). "Increasing evidence indicates that CaSR may play a role in the formation of kidney stones." (PMID 27965733, 2016). "In the kidney, CASR prevents the reabsorption of divalent cations in the cortical thick ascending limb and triggers the inhibitory actions of hypercalcemia on the urinary-concentrating mechanism, subsequently leading to the prevention of kidney stone formation." (PMID 21966463, 2011). "Even though no mutations of the calcium-sensing receptor gene have been found in parathyroid adenomas so far, the Arg990Gly polymorphism of this gene is important for calcimimetic pHPT therapy as a risk factor for nephrolithiasis." (PMID 21461394, 2011). "We aimed to check the association between promoter hypermethylation vitamin D receptor (VDR), calcium-sensing receptor (CaSR), and claudin 14 (CLDN14) genes in recurrent kidney stones." (PMID 35546405, 2022). "Some genes are the most highlighted ones in recurrent kidney stones, like Vitamin D Receptors (VitD R), Claudin 14 (CLDN14), and Calcium-sensing receptor (CaSR)." (PMID 35546405, 2022). "In addition, as 1.25(OH)2D may influence calcium sensing receptor (CaSR) regulation and calcium channel expression, this may well be also a contributing factor for kidney stone formation as it would lead to a lower calcium resorption in the kidney and thus higher urinary calcium." (PMID 35437440, 2022). "We used a CaSR antagonist and activator to evaluate the relationship between MAPK and CaSR in the formation of nephrolithiasis." (PMID 27965733, 2016). "In this study, we investigated the pathogenetic role of CaSR, CLDN14 and VDR genes in kidney stone patients from the Indian population." (PMID 26107257, 2015). "Idiopathic hypercalciuria occurs in up to 50% of individuals with KSD, and negative CaSR allosteric modulators have been suggested as a potential therapy to reduce kidney stones in these individuals by decreasing urinary calcium excretion." (PMID 40372791, 2025). "Earlier study has reported that CLDN14 expression is strongly upregulated by activation of CaSR and dysregulation of renal CaSR-CLDN14 pathway could contribute significantly to the development of kidney stone." (PMID 26107257, 2015). "Further, due to the tissue-specific CaSR-mediated signaling pathways, patients with FHH can manifest uncommon complications like pancreatitis, osteomalacia, and nephrolithiasis that are not expected in this otherwise benign condition." (PMID 27087013, 2016).
Hypercalciuria (47 papers, 2007 to 2026). "Idiopathic hypercalciuria is determined by polymorphic variants/mutations of the calcium sensing receptor (CASR) gene, mutations of SLC34A1, and SLC34A4 genes, polymorphic variants of claudins, genes involved in calcium reabsorption at the tubular level." (PMID 34977081, 2021). "The process of stone formation is frequently related to hypercalciuria, which is associated with renal Ca2+ handling and the renal CaSR." (PMID 33808324, 2021). "CaSR is important for renal Ca2+, as a mutation in this receptor leads to hypercalciuria and calcium nephrolithiasis." (PMID 33808324, 2021). "Evidence has been provided that CaSR polymorphisms such as R990G can increase the susceptibility to hypercalciuria and urolithiasis." (PMID 27679579, 2016). "Second, increased activation of the mutated CASR through extracellular calcium in the distal renal tubules leads to even more pronounced hypercalciuria for any given blood calcium level." (PMID 27803672, 2016). "This meta-analysis revealed that the G allele of CaSR R990G polymorphism increases susceptibility to urolithiasis and hypercalciuria." (PMID 25705702, 2015). "The CaSR decrease renal tubule calcium reabsorption and cause hypercalciuria by suppressing the activity of calcium sensitive potassium channel." (PMID 26107257, 2015). "A number of case-control studies were conducted to investigate associations between CaSR polymorphisms with risks of hypercalciuria and urolithiasis in humans." (PMID 25705702, 2015). "Despite these limitations, the results of the present meta-analysis suggest that the G allele of CaSR R990G polymorphism increases susceptibility to urolithiasis and hypercalciuria." (PMID 25705702, 2015). "The G allele was recognized to cause a gain of CaSR function and increased susceptibility to hypercalciuria." (PMID 25705702, 2015). "This is a case of a novel inactivating point mutation of CaSR gene that determines an atypical clinical presentation of FHH with hypercalciuria." (PMID 25292184, 2014). "Inactivating (loss-of-function) mutations in the calcium-sensing receptor (CaSR) cause autosomal-dominant hypocalcemia and hypercalciuria." (PMID 23991001, 2013). "Children with hypocalcemic hypercalciuria should be evaluated for hypoparathyroidism and autosomal, dominant hypocalcemic hypercalciuria (gain of function mutation in the calcium-sensing receptor)." (PMID 22857835, 2012). "Hypercalciuria was predictive of CASR polymorphism presence (OR = 2.76, p = 0.003)." (PMID 40870022, 2025). "Moreover, an additional distinct subtype of the syndrome, considered as type V, is characterized by an autosomal dominant hypocalcemic hypercalciuria, and it is linked to gain‐of‐function mutations of CASR." (PMID 40893394, 2025). "Furthermore, although one of the typical features of FHH is hypocalciuria, some patients may present with hypercalciuria caused by the distinct functions of the mutated CaSR in renal and parathyroid cells leading to the incorrect diagnosis of primary HPT." (PMID 27087013, 2016). "It is worth noting that hypercalciuria, a disorder predisposing to calcium kidney stones, is vital in the mechanism of urolithiasis; therefore, we performed the first meta-analysis to evaluate the relationships between three CaSR polymorphisms and urine calcium concentration." (PMID 25705702, 2015). "It is therefore difficult to predict the impact of quinazolinones calcilytics on hypercalciuria and renal salt wasting in patients with activating mutations, although the amino alcohol ronacaleret reduced urinary calcium excretion in healthy probands with wt-CaSR." (PMID 25506941, 2014). "Simultaneously, hypercalciuria activates the calcium-sensing receptor (CaSR) in the collecting duct, which inhibits adenylate cyclase and suppresses cAMP-dependent AQP2 trafficking to the apical membrane." (PMID 41393191, 2025).
Hypercalciuria (continued). "The difference is hormonal response between Cldn16 KO and Trpv5 KO mouse models can account for different activation levels of CaSR in the collecting duct, therefore resulting in the different responses to hypercalciuria." (PMID 38339056, 2024). "Gain-of-function mutations in components of the CaSR-signaling pathway result in autosomal dominant hypocalcaemia (ADH, OMIM 601198, 615361), which is associated with hypercalciuria in ~10% of individuals." (PMID 31729369, 2019). "Activating calcium sensing receptor (CaSR) mutations cause autosomal dominant hypocalcemia (ADH) characterized by low serum calcium, inappropriately low PTH and relative hypercalciuria." (PMID 25506941, 2014). "Since CaSR is suggested to promote urine acidification and diuretic effects in response to hypercalciuria in Trpv5 KO mice, changes in the activation level of this receptor due to changes in hormonal response can lead to different overall responses in Cldn16 KO mice." (PMID 38339056, 2024). "Due to severe hypercalciuria, a tonic activation of the luminal CaSR in the collecting duct is expected in this dKO mice model and, quite interestingly, those mice had a strong reduction in total AQP2 expression associated with a significantly higher expression of AQP2-pS261 and ubiquitinated AQP2." (PMID 31717830, 2019). "Indeed, the calcium sensing receptor—or a similar mechanism—has been proposed to mediate urine dilution in hypercalciuria and to play a protective role against intratubular crystal formation." (PMID 30105595, 2018). "In some genetic forms of hypercalciuria, altered regulation of CaSR expression by vitamin D metabolites may be a critical factor contributing to stone formation." (PMID 27679579, 2016). "We discuss briefly the recent developments in Bartter syndrome (and calcium-sensing receptor), and familial hypomagnesemia with hypercalciuria and nephrocalcinosis (FHHNC), which have improved the understanding of calcium homeostasis in this segment of the nephron." (PMID 17464515, 2007). "It has been recently suggested that CaSR expressed at the apical membrane of collecting duct principal cells could mediate the effects of hypercalciuria in reducing vasopressin-elicited osmotic water permeability and urinary concentrating ability by the activation of autophagic degradation of AQP2." (PMID 31717830, 2019). "A mechanistic link between CASR gene activity was suggested by the finding that claudin-14 mRNA levels were lower in the CASR rs6776158 GG homozygous subjects Therefore, in these cases the predisposition to calcium nephrolithiasis is by a mechanism independent of hypercalciuria." (PMID 27679579, 2016). "The calcium-sensing receptor (CaSR) and solute carrier family 26 member 6 (SLC26A6) play key roles in hypercalciuria and hyperoxaluria, respectively." (PMID 41938536, 2026). "Hypercalciuria is a particularly difficult problem in ADH1 due to two independent mechanisms: low PTH and activation of the CASR in the renal TAL." (PMID 27803672, 2016). "By contrast, hypercalciuria is rare in ADH2, suggesting that renal CaSR may preferentially couple to Gq." (PMID 39658204, 2025). "Here, we utilized neomycin, a known CaSR activator, to assess the Ca2+ entry levels in CaG and ACZ-treated WT and KO PT cells to assess the implications of the combined conditions of hypercalciuria and alkalinuria upon the transcellular mechanism of these cells." (PMID 38732005, 2024). "The activated kidney CaSR that can act independently of PTH to directly determine the circulating Ca2+ concentration inhibits the paracellular uptake of cations in the cortical thick ascending limb of the distal nephron and promotes hypercalciuria." (PMID 27679579, 2016). "In the collecting duct principal cells, CaSR is co-expressed with aquaporin-2 (AQP2) on the apical membrane, where it senses extracellular (urinary) Ca2+ and regulates the water reabsorption in order to control hypercalciuria and prevent Ca2+ crystal formation." (PMID 31717830, 2019).
breast carcinoma (46 papers, 2013 to 2026). "In the aspect of the genetic background, only few studies found a correlation between increased breast cancer risk and single-nucleotide polymorphisms (SNPs) of the CaSR gene." (PMID 37511437, 2023). "We genotyped several breast cancer cell lines to determine if they have the wild-type CASR or the mutated CASR." (PMID 35355564, 2022). "The African-American Breast Cancer Epidemiology and Risk (AMBER) study demonstrated that the SNP in CASR rs112594756 presented with a higher odds ratio for estrogen receptor status in breast cancer." (PMID 32117726, 2020). "Regarding breast cancer, some evidences support an association between three different Single Nucleotide Polymorphisms (SNPs) in CasR (rs112594756, rs17251221, and rs1801725) and breast cancer risk, higher aggressiveness and unfavorable outcomes." (PMID 33113952, 2020). "Studies have aimed to find a correlation between breast cancer risk and single nucleotide polymorphisms (SNPs) of the CaSR gene." (PMID 32117726, 2020). "Calcium sensing receptor is associated with cancer cell proliferation and bone metastatic risk in breast cancer patients." (PMID 32931488, 2020). "Earlier studies have suggested that a CaSR reduction increases the lymph node metastasis risk in breast cancer." (PMID 29348629, 2018). "This study aimed to demonstrate in vivo the involvement of the CaSR in breast cancer cells osteolytic potential and to identify potential targets linked to CaSR activity." (PMID 28915604, 2017). "In a similar fashion, the CaSR appears to regulate PTHrP production by breast cancer cells, which causes osteolysis and stimulates the growth of tumor cells, contributing to the pathophysiology of osteolytic bone metastases." (PMID 27746743, 2016). "Breast cancer: A role for a functional CaSR in breast cancer can be inferred from the fact that in premenopausal women serum calcium levels vary inversely with breast cancer risk in a concentration-dependent manner." (PMID 23340319, 2013). "Calcium-sensing receptor Exon 7 variants in normal breast epithelial and breast cancer cells." (PMID 35355564, 2022). "CaSR SNP at rs1801725 was shown to have associated breast cancer with circulating calcium levels." (PMID 32117726, 2020). "A multivariate analysis showed that CaSR was of independent prognostic significance for both overall survival and cause-specific survival of breast cancer patients; the patients with lower expression of CaSR were also significantly associated with distant metastasis-free survival." (PMID 27303307, 2016). "One possibility is that decreased expression of the CaSR may be associated with an increased risk of developing breast cancer but, once breast cancer is established, tumor levels of CaSR may alter behaviors such as the ability to grow in bone." (PMID 27746743, 2016). "In order to examine this question, we first asked whether there was an association between CaSR and PTHrP levels in breast cancers." (PMID 27746743, 2016). "In addition to cell type-specific differences in the expression level of CaSR, the activity of this receptor has also been shown to be modulated by specific mutations, including inactivating mutations in exon 7 of the receptor in breast cancer patients." (PMID 35355564, 2022). "Although pending further investigation, it is also possible that the expression of distinct variants of the receptor at rs1801725 may lead to distinct CaSR signaling and/or tumor progression patterns in specific subtypes of highly heterogeneous cancers such as breast cancer." (PMID 34357109, 2021). "However, whether these high calcium associated breast cancer outcomes are related to the functional status of the calcium sensing receptor (CaSR) remains unclear." (PMID 28764683, 2017). "In vivo studies have shown that overexpression of the CaSR in the MDA-MB-231 breast cancer cell line increases osteolytic potential by increasing osteoclastogenesis." (PMID 37511437, 2023).